C8orf89 (chromosome 8 open reading frame 89)
Tractability: No criterion of Open Targets' tractability assessment is met for any kind of drug.
Gene: Protein-coding gene on chromosome 8 (73,241,331 to 73,259,530, reverse strand). Ensembl gene ENSG00000274443.
Genetic constraint (gnomAD): Loss-of-function variants: 10 observed, 9.5 expected, observed/expected ratio (o/e) 1.05, 90% interval 0.65 to 1.72. That is too few expected variants to judge how well the gene tolerates losing a copy. Missense variants: 106 observed, 112.78 expected, observed/expected ratio (o/e) 0.94, 90% interval 0.8 to 1.11. Synonymous variants: 31 observed, 39.29 expected, observed/expected ratio (o/e) 0.79, 90% interval 0.59 to 1.07.
Homologues: Orthologues: chimpanzee C8H8orf89 (99% identical), macaque C8orf89 (91% identical), pig C8orf89 (76% identical), rabbit C8orf89 (73% identical), dog C8orf89 (70% identical), rat C5h8orf89 (66% identical), mouse 4930444P10Rik (65% identical), guinea pig C8orf89 (61% identical).